S100A8 (S100 calcium binding protein A8)
Diseases named in the same sentence as S100A8 in open-access papers (continued):
Sharing a sentence is not in itself a finding about the gene and the disease.
COVID-19 (continued). "Furthermore, single nucleotide polymorphisms located in IL1RN are associated with COVID-19 severity, and S100A8/A9 appear to be a potential progression biomarker." (PMID 36230912, 2022). "In addition, an increase surge in S100A8 and S100B is associated with mild to severe COVID-19 pathogenesis." (PMID 35892571, 2022). "Genes involved in neutrophil degranulation and/or other neutrophil functions had increased expression levels in patients with severe manifestations of COVID-19, such as S100A8/9 and S100A12, encoding calprotectin and calgranulin, respectively, as recently reported." (PMID 34135895, 2021). "However, no research has yet investigated the association between serum and faecal levels of S100A8/S100A9 in COVID-19." (PMID 34753964, 2021). "The presence of S100A8/A9 in fecal is linked to intestinal inflammation in COVID-19 patients." (PMID 34239729, 2021). "DEFA1 and S100A8/A9 expression levels were significantly higher in patients with fatal outcome (p=0.004; p=0.03 respectively) suggesting that neutrophil activation is associated with mortality in COVID-19 patients." (PMID 34746027, 2021). "Studies have suggested that S100A8/A9 has a regulatory effect on the cytokine storm, which is a defining feature of severe and often fatal COVID-19 cases." (PMID 40742121, 2025). "S100A9 mediates a variety of respiratory diseases, such as chronic obstructive pulmonary disorder (COPD) and infectious diseases, including tuberculosis, influenza and coronavirus disease 2019 (COVID-19) by forming a heterodimer with S100A8." (PMID 39516272, 2025). "Higher levels of S100A8/9 have been observed in severe and fatal patients with COVID-19 needing ICU-level management compared to patients with COVID-19 not requiring ICU admission." (PMID 40124495, 2025). "In many previous studies, S100A8/A9 has been identified as a crucial marker for revealing the mechanism of COVID-19." (PMID 40362649, 2025). "In severe COVID-19, elevated S100A8/9 levels drive emergency myelopoiesis, leading to the generation of immature neutrophil subsets and resulting in dysfunctional innate immune responses." (PMID 41164170, 2025). "S100A8/9 transcripts were also increased in classical monocytes in active and convalescent COVID-19 samples." (PMID 39890933, 2025). "In our study, we observed a significant upregulation of S100A9 and its heterodimer partner S100A8 in PLWH with COVID-19 compared to HCs." (PMID 40568587, 2025). "The plasma of severe COVID-19 patients is also characterized by highly elevated calprotectin, a heterodimer of S100A8 + S100A9 alarmins produced by neutrophils which can facilitate nitrosylation of GAPDH108." (PMID 37147288, 2023). "Consistent with our findings of GRNs from existing scRNA-seq PBMCs, we discovered that the associated TFs were also expressed in the corresponding cell types and upregulated their target genes such as S100A8/A9 in severe COVID-19." (PMID 37936693, 2023). "We also observed that during severe COVID-19, S100A8 and S100A9 were considerably upregulated in multiple other cell types, such as B cells, granulocytes, PB, and DC." (PMID 37936693, 2023). "It is difficult to explain how S100A8 regulates the pathogenesis of COVID-19 because S100A8 plays a critical function in immunological responses." (PMID 35892571, 2022). "A recent study reported that immature neutrophils with elevated calprotectin S100A8/S100A9 plasma levels can be used as robust biomarkers of COVID-19 severity." (PMID 35903092, 2022). "With our design, we were able to confirm well-recognized COVID-19 severity characteristics such as type I interferon dysregulation or the systemic up-regulation of S100A8/A9 genes in monocytes." (PMID 35648852, 2022). "Our results uncover the lncRNA PIRAT (PU.1-induced regulator of alarmin transcription) as a major PU.1 feedback-regulator in monocytes, governing the production of the alarmins S100A8/A9, key drivers of COVID-19 pathogenesis." (PMID 35998224, 2022).
COVID-19 (continued). "RAGE ligands (AGE, S100A8/A9, S100B, amyloid-beta, LPA, HMGB1, C1q, suPAR) and sRAGE are elevated in CKD, COVID-19 and many of the co-morbidities that increase the risk of disease severity." (PMID 36017003, 2022). "Researchers found that in animal models infected with SARS-CoV-2 and COVID-19 patients, the expression level of S100A8 was remarkably increased." (PMID 35928229, 2022). "The treatment of this drug can be suggested as a method for therapeutic purposes while simultaneously detecting abnormal changes in S100A8/9 and neutrophils in the COVID-19 state." (PMID 35185933, 2022). "We found that S100A8/9/12hiHMGB2-expressing cMono correlated with COVID-19 severity and were also increased in sepsis." (PMID 35216673, 2022). "Among the mRNAs up-regulated during COVID-19 (scRNA-seq data), S100A8 and S100A9 experienced the strongest derepression upon PIRAT knockout." (PMID 35998224, 2022). "Serum levels of S100A8/S100A9 are also biomarkers of COVID-19 severity and predictors of subsequent ICU admission." (PMID 36017003, 2022). "Genes differentially expressed by blood monocytes identified S100A8, previously reported in COVID-19 as contributing to the cytokine storm in severe infection." (PMID 33879890, 2021). "Alarmin S100A8 was robustly induced in SARS-CoV-2-infected animal models as well as in COVID-19 patients." (PMID 34220859, 2021). "They identified neutrophils (IFITM2, IFITM1, H3-H3B, SAT1 and S100A8) and macrophage cluster-1 (CCL8, CCL3, CCL2, KLF6 and SPP1) as the main immune cell subsets associated with severe COVID-19 cases." (PMID 34109284, 2021). "The increase in S100A8/A9 during COVID-19 correlates with changes in monocyte and neutrophil subsets associated with the stimulation of emergency myelopoiesis." (PMID 34948277, 2021). "As expected, the core MS1 gene S100A8 was the most significantly up-regulated gene in CD14+ cells generated from HSPCs using severe COVID-19 plasma." (PMID 34103408, 2021). "More recently, S100A8/A9 was found to be upregulated in patients with COVID-19 and expression correlated with disease severity." (PMID 34758843, 2021). "For example, the protein levels of S100A8/A9, which have been found to be up-regulated in severe COVID-19 cases, were significantly elevated in lung tissues." (PMID 34876996, 2021). "Classical monocytes also transcribed several genes encoding for the S100 protein family, such as S100A4, S100A8, S100A9, and S100A12, which were recently implicated in COVID-19." (PMID 34424199, 2021). "Chen and his co-workers reported that the level of S100A8 positively correlated with the Ct value and oxygen demand, indicating the severity of the acute respiratory distress in COVID-19 patients." (PMID 33995121, 2021). "The acute phase response proteins such as SAA-4 and S100A8 were also upregulated in response to COVID-19." (PMID 33995121, 2021). "These proteins are up-regulated in the severe forms of COVID-19, and can induce inflammatory cytokines, influence lipid metabolism, and induce neutrophil activation, as shown for S100A8 and S100A9, thus possibly contributing to amplify the cytokine storm." (PMID 34876157, 2021). "A recent study showed that severe COVID-19 patients release massive amounts of S100A8, accompanied by changes in monocytes and neutrophil subsets." (PMID 33995121, 2021). "Among the identified gene signatures, IFITM2, IFITM1, H3F3B, SAT1, and S100A8 gene signatures were highly associated with neutrophils, while CCL8, CCL3, CCL2, KLF6, and SPP1 were associated with macrophages in severe-COVID-19 patients." (PMID 34220859, 2021). "Other studies have shown that serum levels of S100A8/A9 were significantly elevated in COVID-19 patients and strongly correlated with the severity of clinical manifestations (33, –35)." (PMID 33082228, 2020).
COVID-19 (continued). "Among the identified gene signatures, IFITM2, IFITM1, H3F3B, SAT1, and S100A8 gene signatures were highly associated with neutrophils, while CCL8, CCL3, CCL2, KLF6, and SPP1 were associated with macrophage cluster-1 in severe-COVID-19 patients." (PMID 33138195, 2020). "In individuals who tested positive for COVID-19, S100A8 expression was notably elevated relative to healthy individuals, reinforcing previous findings suggesting that S100A8/A9 can serve as a biomarker for assessing COVID-19 severity and predicting clinical outcomes." (PMID 40362649, 2025). "S100 proteins are emerging as promising biomarkers and therapeutic targets, with significant potential in lung diseases, such as elevated levels of S100A8/A9 (calprotectin) correlating with severe COVID-19 and cytokine storms, which suggests their utility as predictive markers." (PMID 41164170, 2025). "Concurrently, using the ADT information of the COVID-19 data set, the original authors discovered a cell cluster that contains S100A8/9/12hi HMGB2-expressing monocytes and found that patients with a larger proportion of cells coming from this cluster exhibited increased illness severity." (PMID 41256547, 2025). "In particular, they reported that systemic upregulation of S100A8 in peripheral blood monocytes may contribute to cytokine storms often seen in severe COVID-19 patients." (PMID 38798352, 2024). "COVID-19 patients showed high levels of S100A8/A9 correlating with disease severity." (PMID 37275917, 2023). "Because S100A8/A9 is involved in multiple inflammatory conditions,such as lupus and diabetes, it has been detected and quantified inurine samples.35−38 Still, it is unclear whether urine S100A8/A9 levels are indicativeof COVID-19 severity or patient prognosis." (PMID 37787461, 2023). "Our resultssupport the association of serum S100A8/A9 levels with COVID-19 severityand suggest that further investigation of urine S100A8/A9 as a COVID-19biomarker is not warranted." (PMID 37787461, 2023). "Louis, Missouri, to expand the understandingof S100A8/A9 as a prognostic biomarker for COVID-19." (PMID 37787461, 2023). "Moreover, in patients with severe COVID-19, although some inflammatory genes, such as S100A8/A9, were found to be upregulated in both respiratory epithelial and peripheral immune cells, their relative regulators can differ in terms of cell types." (PMID 37936693, 2023). "Notably, S100A8/A9 is key to aberrant neutrophil responses in COVID-19, driving exaggerated innate immune inflammation and uncontrolled pathological damage." (PMID 37828990, 2023). "The predominant enriched transcriptional clusters in human GBM M-MDSCs corresponded to previously observed mononuclear phagocyte states marked by S100A8/9/1249,51–55, which were clinically significant in severe COVID-19, bacterial sepsis, lung cancer, and GBM tissue." (PMID 38234734, 2023). "Nonetheless, these gene expression patterns may suggest a link between tocilizumab effects, IL6R, IL6ST, and S100A8/9 in COVID-19 patients." (PMID 35064122, 2022). "Intriguingly, S100A8 expression is known to be upregulated in severe COVID-19 patients." (PMID 35780158, 2022). "This increase persists over time for S100A8 in the severe compared to the mild COVID-19 group." (PMID 36466858, 2022). "Consistent with the progressive changes in abundance according to COVID-19 severity, the frequencies of cycling cMono and S100A8/9/12hiHMGB2 expressing cMono, and CD1c+ cDCs, were associated with clinical variables relating to oxygenation and respiratory function in hospitalized cases." (PMID 35216673, 2022). "In the context of exhaustive inflammation, we observed that TRAM-mediated STAT1/IRF7 circuitry may be involved in the expansion of Ly6C++ monocytes with elevated induction of S100a8, a key signature gene elevated in septic patients including COVID-19 patients." (PMID 35091696, 2022).
COVID-19 (continued). "Moreover, proteins related to the inflammatory response and tissue injury, including proteins S100-A8, S100-A9, serum amyloid A-1, serum amyloid A-2, and immunoglobulins, were significantly increased in the COVID-19 groups, resulting from SARS-CoV-2 infection." (PMID 35937696, 2022). "S100A8/A9 and neutrophil abnormalities are related to the occurrence of COVID-19, and may serve as a new target for COVID-19 therapeutic intervention." (PMID 35928229, 2022). "Studies indicate that S100A8 can be used as a prognostic marker for COVID-19-positive patients and could be the most effective treatment target for COVID-19 by blocking the S100A8/A9 heterodimer binding to the TLR receptor." (PMID 35892571, 2022). "Similarly, it has been previously reported that upregulation of C-Mo and, in particular, higher numbers of CD14+ CD33+ HLA-DR cells and S100A8/9/12 expressing C-Mo are present in severe/critical COVID-19 and sepsis." (PMID 36969980, 2022). "Mac_S100A8 cluster constituted 10% of the myeloid cells at pre-infection baseline, but was absent on 3dpi and abundantly present at the endpoint suggesting a potential role for these cells in post-acute COVID-19 pathology." (PMID 35115549, 2022). "Additionally, neutrophils in COVID-19 express high S100A8 and S100A9, which serve as alarmins to amplify inflammation." (PMID 35401519, 2022). "Paquinimod treatment could reduce these neutrophils and regain anti-viral responses, unveiling key roles of S100A8/A9 and aberrant neutrophils in the pathogenesis of COVID-19 and highlighting new opportunities for therapeutic intervention." (PMID 34220859, 2021). "Interestingly, the presence of G-MDSCs as well as the production of S100A8/A9 were overrepresented in patients with severe COVID-19 compared to patients with mild disease or healthy controls." (PMID 34473802, 2021). "As calprotectin can regulate the production of TNF-α and CXCL8 and promote NF-κB activation, elevated levels of the S100A8/S100A9 heterodimer may trigger a harmful hyperinflammatory loop in patients with severe COVID-19." (PMID 34471261, 2021). "In contrast, G-MDSC from severe COVID-19 patients had increased expression of genes associated with granulocyte functions/degranulation and chronic inflammation including Arg1, MMP8, MMP9, S100A8 and A9, MPO, IL18RA, elastase, PRTN3 (azurophilic granule protein 7)." (PMID 34341659, 2021). "Single cell RNA sequencing analyses showed the increased presence of dysfunctional neutrophils expressing S100A8, S100A9, DEFA3 and DEFA4 genes in the PBMCs of severe COVID-19 patients suggesting association of the phenotypic alterations in neutrophils with disease severity." (PMID 34746027, 2021). "Interestingly, S100A8/A9 was massively produced by suppressive immature neutrophils in patients with severe COVID-19." (PMID 34473802, 2021). "In addition, in severe COVID-19, the levels of circulating mitochondrial DNA, S100A8/A9, and high mobility group box 1 were also significantly increased and were correlated with inferior clinical outcomes." (PMID 34817280, 2021). "In addition, severe cases of COVID-19 are accompanied with dysregulation of monocyte populations with increased level of S100A8/A9 or calprotectin, which can prime and induce the inflammasome activation." (PMID 34151773, 2021). "The elevated levels of S100A8/A9 in COVID-19 patients, particularly those with severe pneumonia and multi-organ failure, suggest its potential as a biomarker for disease progression, helping to predict which patients may require intensive care or more aggressive treatment." (PMID 41585373, 2025). "Interestingly, it has been reported that S100A8 is upregulated in patients with severe COVID-19." (PMID 36932197, 2023).
COVID-19 (continued). "Transcriptomic changes in COVID-19-related genes within virus-positive cells were highly upregulated in S100A8/A9, mainly in monocytes and megakaryocytes in peripheral blood, which might result in intensive “cytokine storms” that could be observed in severe patients." (PMID 35783255, 2022). "Elevated mRNA expression of S100A6, S100A8, S100A9, and S100P, have been identified in the nasal swabs of COVID-19 patients." (PMID 41164170, 2025). "The expression of S100A9 and S100A8 proteins is increased in various pulmonary diseases, including idiopathic pulmonary fibrosis, COPD, COVID-19 and lung cancer." (PMID 39516272, 2025). "Neutrophils from severe COVID-19 cases exhibit a hyperinflammatory profile, with upregulated expression of IL1β, CXCL10, and S100A8, corroborating the findings of cytokine storm syndromes reported in severe COVID-19." (PMID 39928675, 2025). "S100A8 and S100A9 show the highest hubness in the networks of the four COVID-19 severity groups, particularly the genes that are regulated by a large number of parent genes." (PMID 40362649, 2025). "Transcriptomic analyses have shown overexpression of S100A8, S100A9, S100P and S100A12 in lung tissue from fatal COVID-19 patients." (PMID 41164170, 2025). "Interestingly, many pro-inflammatory genes including S100A8 and S100A9, chemotaxis genes such as CXCR2 and FPR1, and NETosis-associated genes such as TIMP1 were highly expressed in neutrophils of ANPEP-high patients with COVID-19 compared with ANPEP-low patients with COVID-19." (PMID 40168094, 2025). "Using this approach, genes S100A8, IFI27, CLU, IFITM3, and MT-CO1 have been identified as the stable gene panel for the classification of severe COVID-19 patients, utilizing the same training dataset as previously employed." (PMID 39350339, 2024). "C10 monocytes exhibited high expression of S100A family genes, including S100A8 and S100A12, along with low expression of HLA-DR, reminiscent of HLA-DRlowS100Ahigh monocytes in severe COVID-19." (PMID 37337301, 2023). "First, we measured plasma levels of 8 cytokines (IFN-α, IL-1α, IL-1β, IL-10, IL-6, IL-8, S100A8/A9 (calprotectin), and TNF-α), which were shown to be upregulated in the blood of severe COVID-19 patients." (PMID 38082066, 2023). "Thirdly, genes involving in neutrophil-mediated immunopathology (e.g., S100A8, S100A9 and S100A12, etc.)and pro-inflammatory responses were elevated in COVID-19 acute necrotizing encephalopathy patients." (PMID 37848421, 2023). "Elevated S100A8/A9serum levels were observed in ICU patients (n = 49, p = 0.0370) and patients with fatal cases of COVID-19 (n = 76, p = 0.0018)." (PMID 37787461, 2023). "A previous study has reported that ANXA1-FPR1 and S100A8/9-TLR4 are main mediators of cellular communication between lung epithelial cells and myeloid cells, and their disorder may be an important cause leading to immune storm and systemic disorders of lung in severe COVID-19 patients." (PMID 37087411, 2023). "S100A8, MMP-8 and MPO are involved in lung pathology as consequences of lung tissue degradation in tuberculosis, emphysema, COVID-19 or COPD." (PMID 37375484, 2023). "More recently, a study reported that the S100A8 level is robustly upregulated in both SARS-CoV-2 animal models and COVID-19 patients." (PMID 36768433, 2023). "Consistent with published findings,simple main effects analyses showed that S100A8/A9 levels were significantlyelevated in patients that required ICU admission (p = 0.0370) and those with fatal COVID-19 cases (p = 0.0018)." (PMID 37787461, 2023). "A retrospective study, including 121 COVID-19 patients, shows that circulating HMGB1 and S100A8/A9 levels were significantly elevated in ICU-admitted COVID-19 patients (N = 40) compared to non-ICU COVID-19 patients (N = 81)." (PMID 35401579, 2022). "Among the PIRAT-coexpressed genes were the PU.1-dependent alarmins S100A8 and S100A9, which play a key role in COVID-19 (5, –7, 23, 24)." (PMID 35998224, 2022).